CXCL9 (C-X-C motif chemokine ligand 9)
Diseases named in the same sentence as CXCL9 in open-access papers (continued):
Sharing a sentence is not in itself a finding about the gene and the disease.
Cirrhosis (12 papers, 2009 to 2025). A chronic disorder of the liver in which liver tissue becomes scarred and is partially replaced by regenerative nodules and fibrotic tissue resulting in loss of liver function. "The enhanced hepatic expression of IL‐2, IL‐5, IL‐13, or CXCL9 has been described in the context of schistosomiasis progression and generally in cirrhosis." (PMID 40751475, 2025). "In fact, prior work in cirrhosis showed that higher CXCL9 levels predict poorer survival, supporting our findings that CXCL9 and CXCL10 better capture the injurious immune milieu in advanced ALD." (PMID 41373861, 2025). "However, two chemokine ligands, i.e. CXCL9 and CXCL10, were up-regulated, and such an up-regulation was previously associated with liver injury, e.g., cirrhosis and HCC." (PMID 38528259, 2024). "Importantly, our study identified CXCL5, CXCL9, and CXCL10 as universal HCC markers, independent from underlying etiology of cirrhosis." (PMID 36982370, 2023). "Similarly, CXCL11 and CXCL9 were only marginally significant after FDR correction in logistic regression analyses but were both identified as differentiating markers of cirrhosis in CDA analyses." (PMID 34782638, 2021). "In addition, CXCL9, CXCL10, and CXCL11 are related to the migration of TRAIL CD56+bright NK cells that promote liver injury to the liver in chronic hepatitis B-associated cirrhosis." (PMID 36504808, 2022). "In this context, two recent studies have investigated the role of CXCL9 and CXCL11 in patients with cirrhosis receiving TIPS." (PMID 27578545, 2016). "Among all, the top 5 hub genes identified for NAFLD vs. control were CXCL9, NOS2, SERPINE1, FABP4, and LPL, whereas AKR1D1, UGT2B17, CYP26B1, LIPC, and DGAT2 were identified as the top 5 hub genes for the NAFLD vs. cirrhosis group." (PMID 40365443, 2025). "Patients with CXCL9 rs10336 AG genotype had lower odds of significant fibrosis (LSM ≥ 7.1 kPa) [adjusted OR (aOR) = 0.59 (p = 0.016)], advanced fibrosis (LSM ≥ 9.5 kPa) [aOR = 0.54 (p = 0.010)], and cirrhosis (LSM ≥ 12.5 kPa) [aOR = 0.56 (p = 0.043)]." (PMID 28755163, 2017). "Additionally, the top 5 biological functional hub genes in NAFLD vs. control (CXCL9, NOS2, SERPINE1, FABP4, and LPL) and NAFLD vs. cirrhosis (AKR1D1, UGT2B17, CYP26B1, LIPC, and DGAT2) groups were identified through PPI analysis among lipid, immune, and metabolism dysregulated genes." (PMID 40365443, 2025). "Moreover, patients with CXCL9 rs10336 AG genotype had lower odds of significant fibrosis (LSM ≥ 7.1 kPa) [adjusted OR (aOR) = 0.59 (p = 0.016)], advanced fibrosis (LSM ≥ 9.5 kPa) [aOR = 0.54 (p = 0.010)], and cirrhosis (LSM ≥ 12.5 kPa) [aOR = 0.56 (p = 0.043)]." (PMID 28755163, 2017). "Moreover, CXCL9 and Prolactin resulted to be correlated with the transaminases (AST and ALT), thus confirming that these proteins can be considered as predictors of inflammatory activation during the progression of T2D and HCV-related cirrhosis, which leads to the cancer." (PMID 26226632, 2015).
liver disease (12 papers, 2010 to 2025). "Besides, we have found an association between CXCL9-11 polymorphisms and liver disease in human immunodeficiency virus (HIV)/HCV-coinfected patients." (PMID 28755163, 2017). "Recruitment of CXCR3-expressing lymphocytes and NK cells to sites of liver inflammation by the CXCL9–11 chemotaxis has been proposed for several liver diseases." (PMID 39980752, 2025). "In our study, CXCL9 and CXCL10 were associated with mortality and correlated with MELD scores, likely because they reflect the underlying severity of ALD and portal hypertension, whereas IL-6 and IL-8 mainly capture the superimposed acute inflammatory trigger." (PMID 41373861, 2025). "This positive correlation would be consistent with the recent finding that CXCL9 promoted T17 differentiation in a murine model of liver disease." (PMID 35572511, 2022). "In contrast, high CXCL10/IP-10 and CXCL9/Mig levels during HBV infection were correlated with severe liver disease." (PMID 36366543, 2022). "The CXCR3 ligands CXCL9–11 are known to be expressed by hepatocytes, cholangiocytes, and stellate cells in liver disease but less is known about the CCR6 ligand CCL20." (PMID 22796894, 2012). "It is probable that increased cellular accumulation and the elevated production of inflammatory mediators such as IFNγ and CXCL9 as well as others not evaluated by this study accounts for the extent of liver disease in observed IL-10 deficient livers." (PMID 22880122, 2012). "However, to our knowledge, there is no information regarding the relationship between CXCL9-11 polymorphisms and liver disease in HCV-monoinfected patients." (PMID 28755163, 2017). "Patients with advanced liver disease, classified as MELD-Na ≥ 20, MELD3.0 > 19, and CTP class C, as well as poor short-term outcomes, presented with significantly higher CXCL9 and CXCL10 levels compared to their counterparts." (PMID 41373861, 2025). "Based on our statistical analysis, we were indeed able to identify distinct concentration ranges for CXCL9 and CXCL10 that correspond to varying liver disease severity as defined by CTP, MELD-Na, and MELD 3.0." (PMID 41373861, 2025). "While TNF alfa, IL-6, and IL-8 (CXCL8) are markers of the innate immune “storm” (neutrophil-related), CXCL9 and CXCL10 reflect the adaptive immune response (Th1/lymphocytic) as well as hemodynamic severity (portal hypertension)." (PMID 41373861, 2025). "Similar induction of CCL21, CXCL16, CXCL9 and CXCL13 in the liver in other models of hepatic disease suggests that common mechanisms regulate the recruitment of lymphocytes to the liver following inflammation." (PMID 20502518, 2010). "CXCL9 is involved in ALD pathogenesis by orchestrating T-cell recruitment and IFN-gamma-mediated responses; this can limit fibrosis under some conditions, yet high CXCL9 also reflects severe disease (portal hypertension, organ dysfunction) and portends poor prognosis." (PMID 41373861, 2025). "Additionally, CXCL9-11 chemokines have been significantly correlated with the level of hepatoprotective cytokines such as IL6 and IL10, suggesting their involvement in a counter-regulatory response during the progression of liver disease." (PMID 28755163, 2017). "Similarly, CXCL1 and CXCL9 have chemotactic activities and roles in angiogenesis, inflammation and tumor genesis, CXCL12 is related to the HCC metastatic network by recruiting endothelial cell tumor progenitors, and PECAM-1 reflects the liver disease progression." (PMID 26226632, 2015).
ZIKV infection (12 papers, 2018 to 2025). "Our results are consistent with the characteristic pattern of circulating CXCL10, CCL2, and CXCL9 chemokines during ZIKV infection." (PMID 33430059, 2021). "In addition, ZIKV infection caused increased levels of cTnT, cTnI, CK, CK-MB, CCL2, CXCL9, and CXCL10—biomarkers associated with cardiovascular diseases and infarction-like myocardial pathology." (PMID 40762502, 2025). "In our study, levels of several immune markers, such as IFN-α, IL-12, IL-6, IL-17, IL-10, IL-5, IL-2R, ST2/IL-1R4, CCL2, CCL3, CXCL9, M-CSF and E-Selectin, were significantly higher in presymptomatic/asymptomatic ZIKV infection (A-ZIKV group) when compared to the NI control group." (PMID 31748599, 2019). "Adult patients in the acute phase of ZIKV infection produce high levels of chemokines such as CXCL3, CXCL9, CXCL10 and IL15 in the serum, as well as microcephaly babies in the cerebrospinal fluid, especially when developing neurological symptoms." (PMID 36142200, 2022). "Our findings suggest an important role of type-I interferon (IFN) response and chemokines CXCL10 and CXCL9 in the pathogenesis of microcephaly, which may represent a still unaddressed target with the potential to interrupt the destructive CNS inflammation induced by ZIKV infection." (PMID 31474994, 2019). "Importantly, CCL2, CCL5, CXCL9, and CXCL10 were consistently elevated in both serum and heart tissue, indicating a systemic and localized inflammatory response induced by ZIKV infection." (PMID 40762502, 2025). "Interestingly, CXCL9 and CXCL10 were the highest induced mRNA following ZIKV infection and was also induced but to a lesser degree by DENV." (PMID 37022660, 2023). "The downregulation of inflammatory genes CCL18, CCL19, CXCL6, CXCL9, IL6R, IL11, IL24, and Integrin Subunit Beta 3 (ITGB3) with ZIKV infection may reflect placental immune tolerance." (PMID 35304593, 2022). "Interestingly, children with vertically transmitted ZIKV infection presenting microcephaly showed elevated CXCL-10 levels and CXCL-9 in cerebrospinal fluid obtained after birth; however, in our study, only CXCL-10 concentrations were decreased." (PMID 36146688, 2022). "Moreover, ZIKV infection induced an increase in the chemokines CCL3, CXCL9, and CXCL8, while CCL4 and CXCL11 were significantly decreased." (PMID 33430059, 2021). "The samples from pregnant women with ZIKV infection included in this study showed increases in all anti-inflammatory cytokines (IL-10), and some pro-inflammatory cytokines (IL-6, IFN-γ, IFN-α, and IL-17A), chemokines (CXCL10, CCL2, CXCL9, and CXCL8), and receptors (IL-1RA and IL-2R)." (PMID 33430059, 2021).
metastatic melanoma (11 papers, 2009 to 2022). A melanoma that has spread from its primary site to another anatomic site. "Among the CXCL chemokines, CXCL-12/SDF-1 was previously associated with the rejection of metastatic melanoma during IL-2 therapy and together with CXCL-9 through -11 chemokines in association with the rejection of basal cell carcinomas (BCCs) treated with TLR7 agonists." (PMID 19583830, 2009). "Concordant with previous observations, the analyses of metastatic melanoma biopsies showed an association between the presence of CD8 T cells and the expression of a subset of six chemokines (CCL2, 3, 4, 5, CXCL9 and CXCL10)." (PMID 36429101, 2022). "Both CD25 and CXCL9 should be further investigated as therapeutic targets to overcome resistance to CPI treatment in metastatic melanoma." (PMID 35361879, 2022). "Researchers also figured out the combination therapy of CXCL9/10 agonists and immunotherapy drugs improved the overall response rate in metastatic melanoma and epithelial ovarian cancer." (PMID 36561315, 2022). "We evaluated the correlation of EVI2B gene expression in metastatic melanoma samples with the IFN-γ related gene signature (CXCL10, CXCL9, HLA-DRA, IDO1, IFNG, and STAT1)." (PMID 34439264, 2021). "A study looking at metastatic melanoma biopsies showed that up-regulation of several chemokines, including CCL2, CCL3, CCL4, CCL5, CXCL9, and CXCL10 could be correlated with the presence of T cells in the tumor." (PMID 34207884, 2021).
atherosclerosis (10 papers, 2014 to 2024). A disease characterized by the build-up of fatty material and calcium deposition in the arterial wall resulting in partial or complete occlusion of the arterial lumen. "Of these, CXCL9, CXCL10, CCL5, CCL8, CRCL2, Cd74 and IRF8 have previously been implicated in atherosclerosis." (PMID 25478796, 2014). "CXCL11 can be detected in all stages of plaque development, and evidence suggests that together with chemokines, CXCL9/MIG and CXCL11/ITAC, it regulates T-cell trafficking in atherosclerosis." (PMID 36831031, 2023). "These genes included the chemokines CCL5, CXCL10, CCL8, CXCL9, CCRL2, which were also up-regulated in carotid or coronary human plaques, as shown here, and together reflect pro-atherogenic responses in human atherosclerosis." (PMID 25196434, 2014).
cerebral malaria (10 papers, 2012 to 2024). A sequestration of Plasmodium falciparum in the brain, which can cause coma and/or seizures. "Both CXCL9 and CXCL10 play important roles in the inflammation that drives cerebral malaria-associated neuropathology, namely in terms of T cell adhesion to endothelial cells, and recruitment to the brain parenchyma." (PMID 35787830, 2022). "CCR5+CXCL9/10+ MO-DCs are the main DC subset in the CNS of mice with cerebral malaria." (PMID 27808089, 2016). "The relation found between CXCL9 plasma levels, a chemokine implicated in Th1 response, CD8 T cells, and NK cell trafficking and recently reported for its implication in the pathogenesis of pediatric cerebral malaria, and LILRB2 revealed opposite immune mechanisms between D3 and D30." (PMID 38835780, 2024). "During cerebral malaria, the monocyte-derived dendritic cells (MO-DCs) produce CXCL10 and CXCL9, but it is still unclear which APCs are responsible for producing CXCR3 ligands during T. cruzi infection." (PMID 32574175, 2020). "The CXCR3 ligands CXCL9 and CXCL10 are also required for the development of cerebral malaria, but they are expressed in a tissue dependent manner with microglia having increased levels of CXCL9 and astrocytes having increased levels of CXCL10, while the levels of both were elevated in neurons." (PMID 24472559, 2014).
colorectal tumor (10 papers, 2019 to 2025). "This is mediated by IL-17’s signaling to colorectal tumor cells, which leads to the reduced production of CXCL9/10 chemokines." (PMID 31775909, 2019). "IL-17 signals to colorectal tumor cells and inhibits their production of CXCL9/10 chemokines." (PMID 31775909, 2019). "In Visium spatial transcriptomics of human colorectal tumours, there were hotspots enriched in monocyte/macrophage genes (including CD14+CD68+), and expression of CXCL9 and CXCL10 were localised to these regions." (PMID 40523200, 2025). "IL-17 signals to colorectal tumor cells and inhibits their production of CXCL9/10 chemokines, thus inhibiting the infiltration of CD8+ CTLs and Tregs to colorectal tumor cells." (PMID 36195874, 2022). "Specifically, cytokines that were previously shown to correlate with the cytolytic index (C1QA, C1QB, C1QC, CXCL9, CXCL10, CXCL11 and CXCL13), were upregulated in CYT-high colorectal tumors." (PMID 31429779, 2019). "In previous studies showed high expression level of CXCL9 and CXCL10 in colorectal tumors could promoted lymphocytes infiltrate into tumors, and suppressed tumor cells’ growth." (PMID 30973890, 2019). "Signaling of CXCL9/10 through CXCR3 is required for the recruitment of CD8+ CTLs and Tregs, but not Th1 or Th17 cells, to colorectal tumors." (PMID 31775909, 2019).
cutaneous melanoma (10 papers, 2020 to 2025). A primary melanoma arising from atypical melanocytes in the skin. "Studies on cutaneous melanoma showed that the IHC of CXCL9 was significantly elevated in tumor tissues compared with normal controls, and high-CXCL9 mRNA level was related to a better OS compared with the low-CXCL9 group." (PMID 38957805, 2024). "RT-treated patients with low ARID1A expression from other tumor entities, such as skin cutaneous melanoma (SKCM), thyroid carcinoma (THCA), and glioblastoma multiforme (GBM), displayed higher expression of CXCL10, IL-6 and CXCL9." (PMID 38587186, 2024). "Our correlation analysis of the transcriptomic data of 368 cutaneous melanoma samples revealed a positive correlation of PD-L1 to IFN-γ, STAT-1, IFN-γ driven CXCL10 and CXCL9 as well as to acidosis driven MMP9." (PMID 38102680, 2023). "Patients with high expression of CXCL9, CXCL10, CXCL13, CCL4, and CCL5 in SKCM (Skin cutaneous melanoma) had better overall survival." (PMID 36341437, 2022). "primarily identified five chemokine members (CCL4, CCL5, CXCL9, CXCL10, CXCL13) as relevant biomarkers in cutaneous melanoma tumorigenesis and progression." (PMID 36713580, 2022). "In summary, this study mainly identified five chemokine members (CXCL9, CXCL10, CXCL13, CCL4, CCL5) associated with SKCM tumorigenesis, progression, prognosis and immune infiltrations, which might help us evaluate several immune-related targets for cutaneous melanoma therapy." (PMID 32508531, 2020). "Moreover, chemotherapy induces intratumoral expression of CCL5, CXCL9, and CXCL10 in cutaneous melanoma, favoring T cell infiltration and tumor control." (PMID 35292660, 2022). "Intestinal microbes may influence the proportion of CD8+ CTLs that infiltrated cutaneous melanomas, and Lachnoclostridium is positively correlated with the expression of infiltrated CD8+ CTLs and the chemokines CXCL9, CXCL10, and CCL5 in cutaneous melanoma tissues." (PMID 38515134, 2024).
glioblastoma (10 papers, 2015 to 2025). The most malignant astrocytic tumor (WHO grade IV). "Collectively, these findings suggest that FGF21 expression is inversely associated with the risk of developing glioblastoma, whereas an increased risk is linked to elevated levels of CXCL9 and IL-33." (PMID 38784036, 2024). "Transcriptomic analysis showed that FGF21 expression was inversely associated with the risk of developing glioblastoma, whereas an increased risk was linked to elevated levels of CXCL9 and IL-33." (PMID 38784036, 2024). "Using the IVW method, we discovered a possible correlation between an increased risk of glioblastoma and elevated levels of C-X-C motif chemokine 9 (CXCL9) and Interleukin-33 (IL-33) (OR, 1.03; 95% CI: 1.01, 1.06; p = 0.021; OR, 1.03; 95% CI: 1.03, 1.06; p = 0.030)." (PMID 38784036, 2024). "To investigate the role of Cystatin D, FGF21, IL-33 and CXCL9 in glioblastoma, we analyzed the correlation between the expression of these genes and survival prognosis characteristics in patients with glioblastoma." (PMID 38784036, 2024). "Reverse MR and transcriptomic analyses in this study also revealed a potential correlation between glioblastoma, CXCL9, and IL-33." (PMID 38784036, 2024). "The results demonstrated a significant downregulation of FGF21 expression in glioblastoma tissues, whereas both CXCL9 and IL-33 were notably upregulated." (PMID 38784036, 2024). "Moreover, our reverse MR analysis revealed that glioblastoma may contribute to increased concentrations of C-X-C motif chemokine 9 (CXCL9) and Interleukin-33 (IL-33) in the bloodstream." (PMID 38784036, 2024). "Additionally, increased FGF21 expression positively correlated with improved overall survival (OS), whereas increased levels of CXCL9 and IL-33 were associated with decreased OS in patients with glioblastoma, although the difference was not statistically significant." (PMID 38784036, 2024). "Vice versa, transfection of the human glioblastoma cell line U-373 MG with a C/EBPD expression vector led to a significant upregulation of C3, CXCL9, CP, CCL3, TNFAIP6, and IL-6 mRNA levels." (PMID 26230261, 2015). "In previous research on glioblastoma, Qun Chen and colleagues found that EMP3 promotes the migration and M2 polarization of monocyte-derived macrophages and downregulates the production of chemokines induced by interferon, CXCL9 and CXCL10, by macrophages." (PMID 41000385, 2025).